MYC (MYC proto-oncogene, bHLH transcription factor)
Diseases named in the same sentence as MYC in open-access papers (continued):
Sharing a sentence is not in itself a finding about the gene and the disease.
breast cancer (continued). "This was of particular importance considering that ELF5 not only acts as a tumor suppressor by inhibiting the transcription of ER, MYC and Slug in breast cancer but also acts as a carcinogenic factor in basal-like breast cancer cells and endocrine-resistant cells." (PMID 33742100, 2021). "In human breast cancer tissues, the level of c-MYC is positively correlated with that of p97." (PMID 33731668, 2021). "Consistent with evidence that ER can mediate glutamine metabolism in HR+ breast cancer, a number of studies have reported that ERα and/or other commonly activated oncogenes in ER+ breast cancer, including MYC, can directly or indirectly induce expression of CAD." (PMID 34638293, 2021). "Our findings highlight a notable link between serum PVT1 overexpression and breast cancer, lending support to the formerly reported correlation of MYC and PVT1 co-amplification with rapid breast cancer progression and poor clinical survival in postmenopausal women with HER2positive breast cancer." (PMID 33670447, 2021). "Moreover, we analyzed the mRNA expression of ACTL6A and CDK2, the protein expression of MYC in public human breast cancer datasets from TCGA." (PMID 33541412, 2021). "To further assess whether the upregulation of stromal MYC and its target genes is operative in the stromal compartment of human breast tumors, we compared the expression of MYC with the expression of its target genes in human breast cancer patients." (PMID 34169837, 2021). "Importantly, in breast cancer metastasis, c-MYC is involved in the regulation of lncRNAs, e.g., lncRNA SNHG12, a direct transcriptional target of c-MYC112." (PMID 32929060, 2020). "G1 regulators, cyclin D1 and c-MYC, a Wnt target gene, overexpressed in breast cancers." (PMID 33113766, 2020). "We hypothesize that MYC downregulation of Cd47 may contribute to the M1/M2 shift in our models of breast cancer." (PMID 32685002, 2020). "In addition, MYC mRNA expression was lower in breast cancer, head and neck cancer, kidney cancer, lymphoma, and myeloma cancer." (PMID 33193630, 2020). "The molecular action for PIWIL3 and PLD6 in low grade OC could be involvement in growth regulation such as in glioma and mediating downstream pathways for proto-oncogene, MYC, as seen in breast cancer, respectively." (PMID 33374923, 2020). "Given the MYC oncogene is known to control multiple aspects of cell cycle regulation, we were interested in the clinical significance of elevated levels of MYC specifically in breast cancer." (PMID 33143224, 2020). "Recently, it has been hypothesized that an oncogenic event, such as the mutation of c-MYC, is required to facilitate an aberrant increase in RNA pol III activity for the initiation and progression in a model of breast cancer." (PMID 33176745, 2020). "MYC is overexpressed in patients with ER+ breast cancer that is resistant to tamoxifen; this may be related to its roles in the cell cycle, oncogenesis, and tumor progression." (PMID 32340192, 2020). "Furthermore, it has been demonstrated that ABCC1 is a direct c-MYC target in breast cancer and glioblastoma cells." (PMID 32718079, 2020). "To determine whether estrogen signaling promotes MYC expression in human breast cancer, we analyzed the expression of Myc mRNA and ERα protein in a tissue microarray with human breast tissues." (PMID 31978754, 2020). "Pin1 participates in a variety of processes, including cell proliferation, growth suppressor evasion, genome instability and centrosome amplification, and Pin1 acts on its substrates cyclin D1, AKT, ERα, β-catenin, NF-κB, and c-MYC at the tumour initiation stage in breast cancer." (PMID 32010480, 2020).
breast cancer (continued). "Finally, macrophages were polarized using breast cancer tumor-conditioned media (TuCM) to evaluate the effects of MYC inhibition on macrophages in a breast cancer context." (PMID 32685002, 2020). "Similarly, human estrogen receptor-positive breast cancer cells typically displayed elevated levels of Myc protein due to overexpression of MYC mRNA." (PMID 32850392, 2020). "Thus, the WAP-Myc syngrafting protocol is a suitable tool to study the mechanisms of metastasis in MYC-driven breast cancer." (PMID 33127915, 2020). "Abnormal MYC expression is frequently involved in the initiation and development of breast cancer." (PMID 32695665, 2020). "With this data in mind, we first evaluated the association of PML, MYC, and PIM1 in breast cancer." (PMID 31570853, 2020). "Furthermore, genetic or pharmacological inhibition of the spliceosome in vivo impairs survival and tumorigenicity of MYC-dependent breast cancers." (PMID 32006464, 2020). "Factors other than AR may include KLF4 and c-MYC, which were found to be involved in breast cancer stem cell maintenance." (PMID 32781788, 2020). "Specifically in breast cancer, MYC overexpression has been well reported." (PMID 33143224, 2020). "Extra copies of the MYC gene along with extra copies of Pvt1, Ccdc26, and Gsdmc (all located in the 8q24.21 chromosomal region) were shown to be necessary for the formation of mammary tumors." (PMID 32117705, 2020). "Therapeutic regulation of MYC activation may provide new clinical strategies to suppress different oncogenic mechanisms in African American breast cancer patients." (PMID 32873298, 2020). "In our study, we found that targeting CDK7 increased the toxic effect of tamoxifen in sensitive and resistant breast cancer cells as well as in vivo models by targeting important proteins, such as ER and MYC, and essential pathways in breast cancer progression (STAT3 and β-catenin)." (PMID 32340192, 2020). "MYC is a potent oncogene that alone can reactivate the embryonic stem cell-like program in normal and cancer cells that is overexpressed by various mechanisms in more than half of breast cancers; and functionally, MYC indeed contributes to tumor initiation and progression in breast cancer." (PMID 33217982, 2020). "Furthermore, ER regulates the glutamine metabolism by crosstalking with HER2 signaling in a way dependent on c-MYC in aromatase inhibitor-resistant breast cancer cells." (PMID 33489906, 2020). "Interestingly, expression level of OCT4, SOX2and c-MYC was significantly increased in mammospheresand three malignant breast tumors who were under neoadjuvanttherapy (patients I, II and V)." (PMID 31376329, 2020). "We therefore hypothesized that targeted delivery of a MYC inhibitor to established M2 TAMs could reduce polarization toward an M2 phenotype in breast cancer models." (PMID 32685002, 2020). "Although direct targeting MYC for cancer therapy has been challenging, the clinical data shown here would suggest that ATR-Chk1 pathway targeting could be an alternative anti-cancer approach in MYC-amplified breast cancers." (PMID 30746633, 2019). "We next examined whether the AMPK and BCL-2/BCL-XL co-targeting strategy triggers MYC-dependent apoptosis in human breast cancer tissue." (PMID 30728358, 2019). "Notably, no therapeutic potential was observed for the ABn regimen in two breast cancer models with low MYC expression status." (PMID 30728358, 2019). "Whether ATM and ATR expressions influence clinical outcomes in MYC overexpressed breast cancers is unknown." (PMID 30746633, 2019). "In addition to MITF, other amplified and overexpressed genes are HER2 in 15%–20% of invasive breast carcinomas, MYC in 15-20% of breast cancer and several hematological malignancies, EGFR in squamous cell carcinomas, MDM2 in several cancer type." (PMID 31217906, 2019). "Similarly, a transcriptional repressor TRPS1 and MYC are commonly co-amplified in breast cancers and TRPS1 inhibits YAP-dependent TEAD activity by direct binding." (PMID 31212916, 2019).
breast cancer (continued). "The “promoter-enhancer competition” between PVT1 and MYC is currently only found in breast cancer cell lines and, thus, requires further exploration regarding whether this competition commonly exists in other MYC-driven cancers." (PMID 31309249, 2019). "Together, our data show that MYC-ATM co-expression has prognostic significance in breast cancers." (PMID 30746633, 2019). "Therefore, targeting MYC and MYC-regulated enhancers or oncogenic pathways represents potential therapeutic strategies for basal-like breast cancers." (PMID 31013830, 2019). "To this end, we used a non-transformed parental cell (MCF10A) and developed an isogenic panel of cell lines that could meet these standards and model the transformation of breast cancer upon the introduction of deregulated MYC." (PMID 31350286, 2019). "Therefore, CCND1 is highly likely to be the gene that mediates rs614367 breast cancer susceptibility: variants in the enhancer region (either rs614367 or other functional variants) may be hypothesized to drive risk by disrupting E2F1/GATA3/MYC/TCF7L2/ZNF217 binding and affecting CCND1 expression." (PMID 30247654, 2019). "It has been shown that MYC is overexpressed preferentially in TNBCs of the basal like subtype due to mechanisms such as copy number amplification (in ~53% of all basal-like breast cancers), changes in MYC promoter transcriptional regulation and protein stability." (PMID 30076412, 2019). "To investigate the prevalence of TEs in breast cancer-associated TFBSs, we mapped the genome-wide binding sites for C/EBPβ, E2F1 and MYC in MCF7 breast cancer cells by re-analysing publicly available chromatin immunoprecipitation sequencing (ChIP-seq) datasets." (PMID 31061680, 2019). "In addition, c-MYC overexpression leads to a significant increase in CSCs in breast cancer cell lines." (PMID 31428052, 2019). "Together the data show that MYC-ATR co-expression has prognostic significance in breast cancers." (PMID 30746633, 2019). "Additional work is required to establish if XBP1 activates c-MYC expression in breast cancer cells as well, and whether c-MYC regulates IRE1 expression and XBP1 activity in PCa cells." (PMID 30679434, 2019). "Indeed, several splice factors including BUD31, SF3B1 and SRSF1 are known to be gene targets of the oncoprotein MYC and inhibition or knockdown of those in MYC hyperactivated breast cancer cells impairs tumorigenesis." (PMID 31666932, 2019). "HN1 could promote breast cancer progression by increasing MYC activity, and contribute to cell growth and migration in prostate cancer." (PMID 31257225, 2019). "Previous studies have implied that MYC was a target of PIM1 and PIM1 inhibition abrogated the growth of MYC-overexpressing tumors, we detected whether MYC was involved in PIM1-induced breast cancer EMT and stemness." (PMID 30989585, 2019). "Although MYC amplification promotes aggressive breast cancer phenotype, whether ATR and ATM expressions influence pathology and clinical outcomes in MYC overexpressed breast cancers is unknown." (PMID 30746633, 2019). "We then investigated the prognostic significance of MYC-ATM co-expression in breast cancers." (PMID 30746633, 2019). "We conclude that ATR/ATM-directed stratification and personalisation of therapy may be feasible in MYC overexpressed breast cancer." (PMID 30746633, 2019). "In addition, resistance to second-line everolimus (mTORC1 inhibitor) and exemestane (aromatase inhibitor) in women with ER+ breast cancer was shown to occur through upregulation of MYC driving mTORC1 resistance." (PMID 30906568, 2019). "For instance, MYC deregulation is conductive to development and progression in breast cancer." (PMID 31213036, 2019). "Based on a study elucidating the tumor biology of increasing SUV such as MYC-overexpression or centromere protein F-expression, breast cancer with high SUV levels could indicate aggressive tumors." (PMID 30407916, 2019).
breast cancer (continued). "We then investigated the prognostic significance of MYC-ATR co-expression in breast cancers." (PMID 30746633, 2019). "TNBC is a breast cancer subtype with poor clinical outcome and commonly elevated MYC levels." (PMID 30728358, 2019). "In addition, MYC is frequently overexpressed during progression and distant relapse of ER+ breast cancers and predicts poor outcome following adjuvant endocrine treatment." (PMID 30746633, 2019). "Also, high glucose consistently triggered HK2 and LDHA expression and stimulated the USP28/MYC axis in breast cancer cells." (PMID 30688660, 2019). "Importantly, inhibition of G9A unleashes MYC-mediated suppression of these tumor-suppressor genes and reduces tumorigenicity, particularly in basal-like breast cancers." (PMID 31013830, 2019). "Interestingly, the gene sets of HALLMARKS_MYC_TARGETS_V1 were markedly enriched in PC4high breast cancer samples (P < 0.001), indicating that c-Myc was positively correlated with high expression of PC4 in breast cancer." (PMID 30992017, 2019). "MYC transcription itself is also regulated by many signaling pathways, including WNT/β-catenin signaling, which is one of the most frequent abnormalities in human cancers and is associated with poor prognosis in breast cancer." (PMID 31905596, 2019). "For example, semi-selective KDM4 inhibitors that abrogate KDM4B activity have been shown to be efficacious in inhibiting AR-signalling and growth in prostate cancer cells and to be effective in inhibiting the growth of MYC-driven neuroblastomas and breast cancer stem-like cells." (PMID 31390833, 2019). "However, the “promoter–enhancer competition” between PVT1 and MYC is currently only observed in breast cancer cell lines and mutation of the PVT1 promoter is only observed in breast cancer and malignant lymphoma." (PMID 31309249, 2019). "Furthermore, in line with the existing concept of breast cancer cells being addicted to oncogenes such as MYC for their proliferative and survival capacity, few recent studies have reported the dependence of breast cancer on spliceosomal components." (PMID 31666932, 2019). "Accordingly, PIN1 and c-MYC were found co-over-expressed in breast cancer, driving a gene expression pattern largely composed of genes involved in ribosome biogenesis/ translation and metabolism and enriched in poor-outcome breast cancer subtypes." (PMID 30873382, 2019). "Indeed, PVT1 lncRNA has been proven to play an oncogenic function by protecting MYC protein from phosphorylation-mediated degradation in breast cancer." (PMID 31601234, 2019). "(F) Pearson correlation coefficient was calculated between PDGFRB and MYC expression using data derived from panel E. (G) A panel of selected breast cancer and near-normal cell lines was reverse-transfected with 10 nM pooled PDGFRβ siRNAs and cell viability determined after 6 days." (PMID 30777101, 2019). "c-MYC is a crucial oncogenic transcription factor that can regulate many genes involved in multiple cellular processes, including cell growth, cell-cycle control, and DNA repair, and it is highly expressed in basal-like breast cancer." (PMID 30736840, 2019). "The MYC signatures in breast cancer patients and their similarity to diabetes mellitus raised the question whether metabolic re-programming might be identified through the measurement of other bio-chemical intermediates." (PMID 30167086, 2018). "T‐025 strongly suppressed growth of the allograft tumors without inducing body weight losses, suggesting that CLK inhibitors could exert anti‐tumor effects against MYC‐driven breast cancers." (PMID 29769258, 2018). "To assess whether our findings are clinically relevant, we investigated the expression of MYC-dependent oncogenic signature in a database of breast cancer patients." (PMID 29523784, 2018).
breast cancer (continued). "The IHC analysis showed that MYC and DNMT3A were up‐regulated in TNBC tissues than other breast cancer subtypes (H‐score of MYC, ER+, 148.0 ± 12.2; HER2+, 145.2 ± 15.3; TNBC, 182.5 ± 8.3; H‐score of DNMT3A, ER+, 127.3 ± 9.3; HER2+, 150.5 ± 14.6; TNBC, 160.6 ± 7.9)." (PMID 30324719, 2018). "Importantly, the increased expression of CLK2 worsens the survival of MYC‐amplified breast cancer patients, while having a slight effect on the survival of non‐MYC‐amplified breast cancer patients." (PMID 29769258, 2018). "We observed that breast cancer cell lines with both amplified MYC and highly expressed CLK2 were significantly sensitive to other breast cancer cell lines (Fig EV5); however, we did not observe significant difference in cancer cell lines from other original organ types." (PMID 29769258, 2018). "The pathological relevance of the identified MYC signature was further corroborated by the observation that the expression of these genes correlated with reduced metastatic-free survival in patients affected by high-grade breast cancer." (PMID 29523784, 2018). "Finally, we demonstrated in vivo anti‐tumor efficacy of T‐025 in an allograft model of spontaneous, MYC‐driven breast cancer, at well‐tolerated dosage." (PMID 29769258, 2018). "Importantly, upon MYC overexpression we observed a similar phenotype in the luminal breast cancer cell lines MCF7, T47D, and ZR751." (PMID 29523784, 2018). "Importantly, this MYC (up)-YAP (down) signalling axis limits the stem cell features of breast cancer cells, offering new avenues for therapeutic intervention." (PMID 29507319, 2018). "Our analysis of the METABRIC and TCGA datasets support the hypothesis that in human breast cancer, amplification and overexpression of MYC or FAM84B specifically contributes to development of the basal or luminal subtype, respectively." (PMID 30526553, 2018). "Moreover, disease gene ontology analysis revealed that the MYC regulated genes are the signature genes in mammary neoplasms including osteosarcoma, suggesting the potential role of MYC in regulation of cancer cell adhesion and invasion." (PMID 29644114, 2018). "Some subsets of breast cancer, especially MYC-overexpressing tumors most of which are TNBC, show glutamine addiction, which could be a potential therapeutic target." (PMID 29562706, 2018). "In paired analyses of pre- and post-neoadjuvant chemotherapy breast cancer samples, a significant number of cases showed alterations in c-MYC amplification or copy number gain status (14.3% for amplification; 33.6% for copy number gain) with most cases showing positive to negative conversion." (PMID 30420657, 2018). "In addition, RPL5 has been shown to be involved in suppression of MYC expression and RPL5 knockdown is associated with increased MYC expression in breast cancer cell lines." (PMID 30546832, 2018). "PVT1 is reported to stabilize and upregulate MYC protein in breast cancer cells." (PMID 28265576, 2017). "We found breast cancer patients with high HN1 expression had high MYC expression, suggesting HN1 might regulate MYC expression, overexpression of HN1 increased MYC-activating genes expression, and decreased MYC-suppressing genes expression and vice versa." (PMID 28490334, 2017). "In breast cancer, lots of studies have investigated the significance of MYC." (PMID 29212204, 2017). "HN1 promoted the progression of breast cancer through upregulating MYC." (PMID 28490334, 2017). "As a result, we examined the correlation between p62 and MYC in breast cancer cell lines in vitro." (PMID 27345399, 2017). "TIM exerts its function in breast cancer by upregulation of the oncogene MYC." (PMID 28464854, 2017). "Consequently, in the present study, we evaluated the expression of PCAT-1 and its relation with MYC transcript levels in a population of Iranian breast cancer patients." (PMID 28989584, 2017).